CD47 (CD47 molecule)
Diseases named in the same sentence as CD47 in open-access papers (continued):
Sharing a sentence is not in itself a finding about the gene and the disease.
tumor (continued). "Interestingly, CD47 expression correlates with both CD44 expression and EMT, suggesting CD47 as a promoter of cancer cell stemness, tumor spreading, and resistance to PD-1/PDL-1 inhibitors." (PMID 32962159, 2020). "Blockade of the CD47–SIRPα interaction synergizes with both tumor-specific antibodies and ICIs by effectively reprogramming the myeloid compartment toward a proinflammatory phenotype improving tumor cell phagocytosis, antigen presentation, and T cell priming." (PMID 33256806, 2020). "For example, immune cells or antibodies that inhibit tumor cell-expressed CD47 could be used to reduce the growth and spread of tumors with high expression of CD47, providing a feasible immunological target for anti-tumor therapies." (PMID 32082311, 2020). "Exploiting this mechanism, SIRPα competitively inhibits the CD47 protein on tumor cells." (PMID 33126572, 2020). "Increased SLAMF7 expression on either tumor or immune cells may govern a macrophage’s ability to engulf hematopoietic tumor cells in response to CD47 blockade, although this result has been called into question." (PMID 35582455, 2020). "Finally, nine clones stably producing antihuman CD47 antibodies, specifically binding to CD47 positive tumor cells were obtained." (PMID 33469516, 2020). "In summary, our results demonstrate that vaccination with CD47-deficient tumor cells induces strong antitumor immunity, revealing that removing cell surface expression of CD47 may significantly increase the immunogenicity of whole tumor cell vaccines." (PMID 31996683, 2020). "However, in the present study, we showed that CD47 can also regulate tumor progression in an immune-independent manner." (PMID 32226539, 2020). "In addition, blocking CD47 can also promote macrophages or dendritic cells (DCs) to stimulate tumor-specific cytotoxic T cells, which can eventually clear CTCs." (PMID 31980023, 2020). "Moreover, adaptive immune response, especially that mediated by CD8+ T cells, plays a critical role in anti-CD47-blockade-induced tumor inhibition." (PMID 32536914, 2020). "Additionally, the blockade of CD47 interaction suppresses tumor growth due to increased T cell function and thereby decreasing other suppressive immune markers in human head and neck squamous cell carcinoma." (PMID 32882841, 2020). "Besides serving as SIRPα liangd to initiate inhibitory signal for macrophage phagocytosis against self cells, CD47 has been shown as a suppressor for tumor metastasis, and targeting it presents an potential and effective therapeutic strategy." (PMID 32576895, 2020). "Interestingly, the CD47 blockade in their study reduced irradiation-induced apoptosis in the tumor cells as part of the radioprotective effect of CD47 blockade." (PMID 31547758, 2020). "CD47 expression is a well-known strategy by which tumor cells escape immunosurveillance." (PMID 33256070, 2020). "CD47 blockade may also trigger T cells via stimulator of interferon genes (STING)-based cytosolic sensing of tumor cell DNA." (PMID 35582455, 2020). "Thus, it would be ideal for CD47 blocking cancer immunotherapy to focus on the tumor site and avoid interactions in the immune milieu of the other sites." (PMID 32999291, 2020). "However, the nature of CD47 blockade mediated antitumor effect appears to vary across different mouse genetic backgrounds and tumor models." (PMID 32198351, 2020). "The rank order is somewhat reminiscent of tumor mutational burden, suggesting there may be a correlation between tumor immunogenicity and CD47 expression." (PMID 35582455, 2020). "CD47 expression is unregulated on tumor cells, but its ubiquitous expression in normal tissues may create an ‘antigen sink’ that could decrease the therapeutic effects of anti-CD47 antibody." (PMID 31931812, 2020). "Tumor CD47 levels above 1% and 50% were found in 84% and 65.7% of patients, respectively." (PMID 32043750, 2020). "The anti-CD47 treatment significantly reduced in vivo tumor growth." (PMID 32477352, 2020).
tumor (continued). "Researchers have explored blocking CD47 to induce a wide range of anti-tumor immune function." (PMID 33256070, 2020). "Importantly, when peripheral blood and tumor tissue were compared, CTCs and primary tumor cells presented similar CD47 and PD-L1 expression rates; however, the positivity concordance was low." (PMID 32041353, 2020). "⁣Recently, CD47 has been shown to play a role as a signaling receptor, involving a number of cell physiological processes.⁣⁣ This review provides a comprehensive survey of the signaling pathways triggered by CD47 ligand-mediated cell death in tumor cells." (PMID 33224442, 2020). "Results from additional future clinical studies will demonstrate whether targeting the CD47-SIRPα axis in a clinical setting indeed will activate both innate as well as adaptive anti-tumor immunity." (PMID 32983165, 2020). "Similarly, CD47 and in particular, CD47high expression, was more frequently detected on CTCs compared to tumor cells in the corresponding metastatic sites." (PMID 32041353, 2020). "Several CD47 antibodies are currently being investigated in preclinical studies or Phase I & II clinical trials; however, rather than the anti-angiogenic effect, these mimetics are sought after to overcome immune evasion of the tumor cells expressing CD47." (PMID 32357492, 2020). "High number of iNOS+ M1-like macrophages, both in the center of the tumour (CT) and invasive margin (IM), was significantly associated with improved survival (p = 0.009) while high expression of IDO1 or CD47 in the malignant cells was associated with worsened prognosis (p = 0.018, p = 0.046)." (PMID 31358801, 2019). "Moreover, the administration of CD47-blocking antibodies or targeted inactivation of the Cd47 gene in humanized mouse models markedly inhibited SCLC tumor growth." (PMID 32082304, 2019). "Indeed, anti-CD47 treatment induced a significant increase of in vivo tumor cell phagocytosis by TA-MG (2.7% control versus 13.3% treated, P < 0.0001) as assessed by the presence of GFPhighRFPnegativeEBFP2+ microglia." (PMID 30602457, 2019). "Therefore, blocking CD47-SIRPα signaling has been found to increase macrophage ability to phagocytose tumor cells." (PMID 31629410, 2019). "In agreement with which, activating macrophages by antibodies targeting CD47-SIRP interaction could effectively inhibit tumor growth in both animal experiments and clinical trials." (PMID 31681557, 2019). "Our results also raise the question of the function of CD47 in the context of tumor relapse." (PMID 30814491, 2019). "After orthotopic injection of T387 tumor cells into either NSG-Ccr2RFP/wt-Cx3cr1GFP/wt or NSG-Ccr2RFP/RFP-Cx3cr1GFP/wt mice and confirmation of tumor engraftment via bioluminescence imaging we started treatment with anti-CD47 (250 μg Hu5F9-G4 three times a week) or human IgG control." (PMID 30602457, 2019). "These experiments unveiled the possible elicitation of immune memory by CD47−/− tumor cells." (PMID 31882679, 2019). "In A549 xenograft model, tumor volume presented that targeting VEGF and CD47 by VEGFR1-SIRPα could elicited potent anti-tumor effect." (PMID 31829270, 2019). "Interestingly, we constantly observed an increase in tumor infiltrating NK cells in the CD47−/− vaccinated mice." (PMID 31882679, 2019). "CD47 is expressed in endothelial cells, macrophages, and also in tumour cells." (PMID 30850588, 2019). "The joint blockade of the CD47-SIRPα and PD-1-PD-L1 interactions might have a synergistic effect in the elimination of tumor cells." (PMID 31921125, 2019). "In particular, promotion of tumor cells elimination by phagocytosis could be successfully achieved through the administration of anti-CD47 mAbs." (PMID 32082304, 2019). "Strikingly, we could capture a high proportion of microglia phagocytizing living tumor cells in real time upon anti-CD47 treatment." (PMID 30602457, 2019).
tumor (continued). "We hypothesized that these CD47 edited vaccines induce a tumor suppressive environment to suppress or reduce the tumor progression." (PMID 31882679, 2019). "Thus, the decrease in CD47 levels upon VDAC1 depletion would be expected to enhance anti-tumor immunity." (PMID 31661894, 2019). "Then, we speculated that inhibition of CD47 could be sufficient to extend an anti-tumor response during anti-angiogenic treatment." (PMID 31829270, 2019). "Evidence has accumulated that anti-CD47 targeting can induce macrophage phagocytosis of tumor cells and may improve cell-mediated immune response." (PMID 31771616, 2019). "In particular, our findings of overexpressed CD47 in transcriptomic analysis of patients with EGFR-mutated NSCLC, as well as in tumor cell lines acquiring EGFR TKI resistance, identify CD47 as target to be further explored for the immunotherapy treatment of naïve and resistant EGFR-mutant NSCLCs." (PMID 32082304, 2019). "Interestingly, CD47 is also known as a key immune checkpoint which is highly expressed on tumor cells, making tumor cells resistant to host immune surveillance." (PMID 30872703, 2019). "We found that tumor CD47 expression (HR = 1.703; p = 0.038), CD68+ M (HR = 1.853; p = 0.012), CD163+ M2 (HR = 1.898; p = 0.014), tumor diameter (HR = 1.626; p = 0.047), grade (HR = 1.745; p = 0.011), and N stage (HR = 1.831; p < 0.001) were independent factors associated with OS." (PMID 31771616, 2019). "Regardless, the broad expression of CD47 is thought to present an antigen sink on non-tumor tissue which remains a potential issue that could affect the bioavailability of the drug and thus its dosing strategy." (PMID 31801627, 2019). "Consequently, CD47 blockade enhances tumor cell phagocytosis by TAMs, improves survival in various murine cancer models, and is currently being tested in multiple clinical trials." (PMID 30938231, 2019). "The combination of ICD induction and CD47 blockade improved DC maturation, T cell-mediated response, and antitumor immunity, which ultimately resulted in the regression of tumors, tumor metastasis, and prevention of tumor relapse." (PMID 31754376, 2019). "For instance, immunotherapies combining targeting CD47/signal-regulatory protein alpha (SIRPα), an innate anti-phagocytic axis between tumor cells and macrophages were shown to elicit synergistic anti-cancer activities in both hematologic malignancies and solid tumors." (PMID 31205619, 2019). "As immunotherapeutics directed against tumor-expressed CD47 are currently being tested in clinical trials, impaired wound healing may be an unintended consequence in cancer patients undergoing surgical resection, particularly in the gastrointestinal tract." (PMID 31676794, 2019). "However, the summed tumor area was 1.8‐fold reduced in CD47 mAb‐treated mice (P = 0.01) and 5‐fold reduced in doxorubicin plus CD47 mAb‐treated mice (P = 0.002)." (PMID 31376208, 2019). "Dendritic cells were also involved in CD47 blockade-induced anti-tumor effect in NSCLC." (PMID 31829270, 2019). "Additionally, the tumor-immune biology of CD47 is complex and involves its other ligand thrombospondin-1 (TSP1)." (PMID 31276567, 2019). "Blocking the CD47-SIRPα interaction by using an anti-CD47 antibody could abrogate the suppression of macrophage phagocytosis from CD47 on tumor cells." (PMID 31781673, 2019). "Furthermore, we determined the suppression of tumor progression by treating tumor mice with CD47−/− vaccines." (PMID 31882679, 2019). "CD47 (Cluster of differentiation 47)/SIRPα (signal-regulatory protein alpha), an innate negative immune regulatory axis that transmits “don’t eat me” signal to macrophages and confers tumor cells resistant to immune surveillance." (PMID 31829270, 2019).
tumor (continued). "T-cell-derived exosomes have been shown to contain thrombospondin-1 and its receptor CD47, which promote endothelial cell responses to vascular endothelial growth factor (VEGF) and accelerate tube formation via VEGF signaling, which suggests a role for exosomes in CD47-dependent tumor angiogenesis." (PMID 31615107, 2019). "Similarly, even in the absence of a functioning Ccr2 receptor, inhibiting peripheral macrophage infiltration, anti-CD47 treatment was efficacious and reduced tumor burden significantly as indicated by bioluminescence." (PMID 30602457, 2019). "It should be noted that we could not elucidate the molecular mechanism and the role of CD47 in the acquisition of tumour seeding ability; therefore, additional investigations of CD47 functions are required." (PMID 31273952, 2019). "CD47 blockade enhances the engulfment of tumor cells by antigen-presenting cells (APCs), enabling the processing and presentation of tumor antigens as peptides in the groove of major histocompatibility complex (MHC) class I molecules for subsequent cross-priming and CD8 T-cell activation." (PMID 30674867, 2019). "P962 and P989 nude mice treated with anti-CD47 mAb had reduced tumor burden." (PMID 31771616, 2019). "While CD47 serves as a macrophage checkpoint, blockade of CD47 may also lead to an adaptive anti-tumor immune response as well." (PMID 32038992, 2019). "The expression of CD47 in parental tumor and xenograft was confirmed by IHC." (PMID 31771616, 2019). "Upon macrophage or dendritic cell-mediated phagocytosis of cancer cells by CD47 blockade, these phagocytes may present tumor antigens to T cells to induce anti-cancer T cell responses." (PMID 32038992, 2019). "The overexpression of CD47 on numerous human cancers suggested that tumor cells may evade phagocytosis and clearance by upregulating CD47 expression." (PMID 31801627, 2019). "Next, we wanted to test whether the subsets of Mo/MΦs were able to phagocytose tumor cells and whether blocking the interaction between SIRPα and CD47 altered the phagocytosis of each subset." (PMID 31611550, 2019). "However, when we gated on total tumor cells, we found 60% tumor cell death in the presence of CD47 mAb as compared to 15% tumor cell death in the presence of control antibody." (PMID 30674867, 2019). "The survival rate of mice treated with irradiated CD47−/− 3BD9 cells improved marginally – 10-day increase in survival, and there was a significant delay in tumor growth – 1.5-fold reduced tumor sizes, similar to the trend observed in the prophylactic vaccination regime." (PMID 31882679, 2019). "Moreover, we used the limited dilution assay in vivo to evaluate the effect of CD47 in BCSCs on tumour formation." (PMID 31273952, 2019). "In addition, syngeneic immunocompetent tumor model was established to confirm the relevant of macrophage and CD47 was also evaluated in LLC tumors." (PMID 31829270, 2019). "The enhanced anti-tumor response with agents blocking the SIRPα-CD47 interaction may arise from the activation of multiple DC subsets (i.e. shown by increased CD86 expression) that is seen within the spleen (data not shown)." (PMID 31801627, 2019). "Moreover, they showed CD47 antibody Hu5F9-G4 as an immunotherapeutic drug for SCLC can eradicate tumor cells by promoting macrophages phagocytosis." (PMID 31629410, 2019). "The results show that knockdown of CD47 significantly impairs THBS1-induced tumour cell invasion." (PMID 30850588, 2019). "In summary, our study has shown that the tumor expression of CD47 correlated with the levels of tumor-infiltrating macrophages and may serve as an independent prognostic marker in patients with PDAC." (PMID 31771616, 2019). "Besides, CD47 blockade inhibited the growth of the EC tumors in vivo and increased the infiltration of macrophages with antitumor ability in the tumor microenvironment (TME)." (PMID 30525058, 2018). "The CD47 overexpression was responsible for immune suppression and tumor progression in EC." (PMID 30525058, 2018).
tumor (continued). "Our CD47 tumor targeting SERS nanoparticles could be applied topically to a number of these tissues during intraoperative tumor resection." (PMID 30463284, 2018). "CD47 is frequently overexpressed by cancer cells of multiple tumor types." (PMID 30355585, 2018). "Hence, it is likely that in vivo systemic anti‐CD47 mAb administration will lead to less frequent contact with macrophages and tumor cells, limiting its effect on macrophage phagocytosis." (PMID 30460349, 2018). "Consequently, we investigated the tumor targeting and imaging potential of CD47-targeted SERS nanoparticles in cells and on excised preclinical tissue samples." (PMID 30463284, 2018). "Similarly, CD47 blockade in mouse studies inhibits the growth of human tumor xenografts and promotes survival." (PMID 30133535, 2018). "On evaluating gene array analysis of nonimmunogenic AgN2a cells compared to the parent immunogenic Neuro2a cell line, we identified down-regulation of several tumor immunosuppressive pathways, including PD-L1 (3.6-fold), CD47 (3.3-fold), CD74 (6-fold), and CD40 (2.3-fold)." (PMID 29377881, 2018). "Blocking the SIRPα–CD47 innate immune checkpoint with ADU-1805 may modulate myeloid cells in the tumor microenvironment and promote antigen presentation and cross-priming of dendritic cells." (PMID 30400822, 2018). "Modulation of the anti-tumor immunity by CD47 in T cells by this pathway has been described." (PMID 32984773, 2018). "Finally, we show that tumor-directed blockade of CD47 via biAbs can increase the therapeutic effect of standard of care oncology treatments such as PD-L1-blocking antibodies and cyclophosphamide." (PMID 31544856, 2018). "The antibody binding of CD47 promotes tumor cell phagocytosis by macrophages, neutrophils and DCs." (PMID 30355585, 2018). "In the past 10 years, we and other laboratories have shown that anti-EGFR, anti-HER2, anti-CD20, and anti-CD47 in combination with immune checkpoint blockade could have synergistic effects in host adaptive anti-immune responses and tumor eradication." (PMID 30533489, 2018). "CD47, a transmembrane protein, has been found to be overexpressed in many tumor cells." (PMID 29329591, 2018). "Liu X, Kwon H, Li Z, Fu Y. Is CD47 an innate immune checkpoint for tumor evasion?" (PMID 30400835, 2018). "Additionally, Liu and colleagues demonstrated that anti-CD47-mediated tumor rejection required the activation of T cells." (PMID 29329591, 2018). "It has been shown that blocking CD47–SIRPα interaction could facilitate phagocytosis of tumor cells and promote antitumor immune response." (PMID 30105024, 2018). "SIRPα immunoregulatory activity on myeloid cells is activated by binding of its ligand CD47, and blockade of the pathway may enhance anti-tumor immunity." (PMID 30400822, 2018). "For instance, some anti-CD47 antibodies could induce the apoptosis of tumor cells directly in several malignancies." (PMID 30525058, 2018). "Our data also demonstrate that FusOn-CD47-Luc persisted longer than FusOn-Luc after the viruses had reached to the tumor site after systemic delivery or after being injected directly into the tumor tissue." (PMID 30349648, 2018). "In addition, when studied in tumor models in immunocompetent animals, the induction of adaptive immune responses in mediating therapeutic efficacy of CD47 neutralization has been observed." (PMID 31544856, 2018). "One mechanism inhibiting the innate response is the presence of the macrophage inhibitory molecule, signal regulatory protein-α (SIRPα), on tumor-associated macrophages (TAMs) and its cognate ligand cluster of differentiation 47 (CD47) on tumor cells in the tumor microenvironment." (PMID 30062558, 2018). "This may be accompanied by a downregulation of CD47, which promotes the phagocytosis of tumor cells." (PMID 30373228, 2018).